PPARD (peroxisome proliferator activated receptor delta)
Diseases named in the same sentence as PPARD in open-access papers (continued):
Sharing a sentence is not in itself a finding about the gene and the disease.
nonalcoholic fatty liver disease (10 papers, 2015 to 2023). "Therefore, we sought to test the hypothesis that PPARδ agonism may carry a risk of promoting hepatic fatty accumulation similar to Nonalcoholic Fatty Liver Disease (NAFLD)." (PMID 26604919, 2015). "For example, chronic dietary capsaicin intake prevented non-alcoholic fatty liver disease (NAFLD) in mice through TRPV1-mediated peroxisome proliferator-activated receptor δ (PPARδ) activation." (PMID 37998493, 2023). "Consequently, fimasartan ameliorates nonalcoholic fatty liver disease mainly through the activation of oxidative metabolism represented by PPARδ-AMPK-PGC-1α pathway." (PMID 28386270, 2017). "PPARδ is the Food and Drug Administration (FDA) approved drug target, while PPARγ have been investigated in several clinical trials for their potential in treating non-alcoholic fatty liver disease (NAFLD)." (PMID 32784653, 2020).
diabetic cardiomyopathy (9 papers, 2010 to 2020). Diabetic cardiomyopathy is a disorder of the heart muscle in people with diabetes. "Induction of cardiac angiopoietin Like 4 (Angptl4) via PPARδ activation in the heart is essential in protecting against FA-induced oxidative stress, a key mechanism behind diabetic cardiomyopathy." (PMID 31032335, 2018). "Second, according to our findings, it is concluded that the myocardium protective effect of PPARδ in diabetic cardiomyopathy is regulated by STAT3 and we believed that it is indirectly through ROS reduction." (PMID 27519769, 2016). "PPARδ signaling is impaired in the heart under various pathological conditions, such as pathological cardiac hypertrophy, myocardial ischemia/reperfusion, doxorubicin cardiotoxicity and diabetic cardiomyopathy." (PMID 31032335, 2018). "Our previous studies have showed that activation of PPARδ by cardiac agent may improve diabetic cardiomyopathy in type-1 diabetic rats." (PMID 24689053, 2014).
experimental autoimmune encephalomyelitis (9 papers, 2009 to 2024). An autoimmune demyelinating disease of the central nervous system that is produced experimentally in animals by the injection of homogenized brain or spinal cord in Freund's adjuvant. "The inhibitory effect of PPARD agonist was also found to be associated with an increase of cytokine IL-4 and IL-10 expression and decreased IL-12 and IL-23 expression in the CNS confirming the modulatory effect of PPARD agonist in experimental autoimmune encephalomyelitis." (PMID 34394070, 2021). "For example, deletion of either PPARγ, PPARδ, or LXRα/β results in aggravated disease progression in experimental autoimmune encephalomyelitis (EAE), the animal model of Multiple Sclerosis." (PMID 28926619, 2017). "Kanakasabai and co-workers showed that PPARD agonist (GW501516 and L165041) ameliorates the experimental autoimmune encephalomyelitis in C57BL/6 mice by inhibiting T helper type 1 (Th1) and Th17 responses." (PMID 34394070, 2021).
Sepsis (9 papers, 2012 to 2024). Sepsis is defined as life-threatening organ dysfunction caused by a dysregulated host response to infection. "In a mouse model of sepsis, LPS administration rapidly caused downregulation of PPARα, PPARδ, as well as isoforms of thyroid hormone receptor (TR) and RXR (which are required for PPAR transcriptional activity) in the heart." (PMID 34575939, 2021). "With respect to pre-clinical lung injury and sepsis models, upregulation of PPARδ signalling has been shown to play an important role in LPS-induced ALI and in caecal ligation puncture-induced sepsis." (PMID 34831203, 2021). "Another study reported increased PPARδ at 6 hours after LPS-induced sepsis and unchanged PPARδ at 12 and 24 hours." (PMID 26713088, 2015). "Whether these observed effects of PPARδ are relevant to skeletal muscle in terms of inflammation and substrate oxidation during sepsis and related conditions remains to be determined." (PMID 34575939, 2021). "Thus, it is possible that these rapid decreases in the expression of key genes, including PPARα and PPARδ, are important in driving the reductions in cardiac fatty oxidation and myocardial dysfunction in sepsis." (PMID 34575939, 2021). "Cardiac PPARδ expression is decreased at 4 and 16 hours after LPS-induced sepsis." (PMID 26713088, 2015). "During sepsis, however, declines in PPAR activity may underlie some of the declines in FFA oxidation in various tissues, indicating that there may be some benefit to PPARδ agonism during these conditions." (PMID 34575939, 2021). "Contrarily, treatment with PPARδ agonist GW0742 attenuated LPS-induced cardiac dysfunction and improved survival after cecal ligation and puncture-induced sepsis." (PMID 26713088, 2015). "In a model using cultured muscle cells, one group tested the hypothesis that PPARδ upregulates FOXO1 activity in muscle, thereby upregulating MAFbx and MuRF1 expression during sepsis and glucocorticoid treatment." (PMID 34575939, 2021).
cholangiocarcinoma (8 papers, 2007 to 2024). A carcinoma that arises from the intrahepatic biliary tree (intrahepatic cholangiocarcinoma) or from the junction, or adjacent to the junction, of the right and left hepatic ducts (hilar cholangiocarcinoma). "Overexpression of PPARδ in human cholangiocarcinoma cells has been shown to create a positive feed-forward loop that potentiates the actions of Wnt/β catenin signalling." (PMID 23226273, 2012).
Cognitive impairment (8 papers, 2011 to 2024). Abnormal cognition is characterized by deficits in thinking, reasoning, or remembering. "PPARδ-deficient mice showed cognitive impairment associated with increased cytokine levels, NF-κB activation, and astrogliosis." (PMID 39431021, 2024). "Genetic deletion of PPARδ leads to cognitive impairment with increased levels of enzymes involved in Aβ deposition, tau hyperphosphorylation, neuroinflammation, and astrogliosis." (PMID 39431021, 2024). "The other PPARδ agonist GW0742 also improved MPTP-induced cognitive impairment by suppressing oxidative damage and DNA fragmentation in a rat model of PD." (PMID 35624674, 2022). "It is important to investigate if, similar to PPARγ, PPARδ can modulate radiation-induced cognitive impairment." (PMID 22135673, 2011). "To examine if PPARδ agonist 5a could alleviate AD-like pathology based on its anti-inflammatory properties, we investigated the therapeutic efficacy of 5a using mice with scopolamine-induced cognitive impairment and 12-month-old APPswe/PSEN1dE9 (APP/PS1) double transgenic mice." (PMID 39431021, 2024). "The key findings of the current study are that 3xTgAD mice display cognitive deficits and impaired synaptic plasticity that can be rescued by AU9 through activation of PPARδ and partially PPARγ." (PMID 37190025, 2023). "Treatment with the PPARδ agonist, L-160,043, prevented STZ-induced neurodegeneration and ameliorated cognitive impairment as evaluated by the Morris Water Maze task." (PMID 22135673, 2011). "PPARδ activation prevents the increase in IL-1 gene expression and pERK protein but does not rescue neurogenesis and hippocampal-dependent cognitive impairment." (PMID 35955439, 2022). "Although studies have not examined if PPARδ agonists can modulate radiation-induced cognitive impairment, data demonstrate that PPARγ can ameliorate or prevent radiation-induced cognitive decline." (PMID 22135673, 2011). "In addition, neither PPARα nor PPARδ activation improved hippocampal-dependent cognitive impairment in rats, which is not compatible with reduced neuroinflammation and fewer activated microglia in the hippocampus." (PMID 35955439, 2022). "A model of PPARδ knockout mice with dietary administration of PPARδ agonist, GW0742 sucessfully inhibited neuroinflammation but did not restore neurogenesis or prevent the early-delayed cognitive impairment." (PMID 26610477, 2015).
depression (8 papers, 2015 to 2025). "Specifically, the hippocampal genetic knockdown of PPARD has been shown to cause depression-like behaviors and neurogenesis suppression, suggesting that PPARD plays a crucial role in neurogenesis and regulates both depression and memory." (PMID 33968145, 2021). "PPARD activation also stimulates the biosynthesis of tetrahydrobiopterin, which was implicated to play a role in clinical depression." (PMID 33968145, 2021). "In the present study, changes in 5-HTT expressions were associated with PPARδ expression in both stress-induced depression mice and PPARδ-silenced mice." (PMID 29070884, 2017). "The effects of telmisartan in the improvement of depression induced by UCMS seem to be associated with the selective enhancement of PPARδ and 5-HTT expression levels." (PMID 29070884, 2017). "Although the deficiency of PPARD might lead to depression-like behaviors and promote the development of MDD, it may not naturally happen in the majority of MDD patients." (PMID 33968145, 2021). "It indicated that PPARδ deficiency correlated with the development of depression." (PMID 29070884, 2017). "It should be noticed that in addition to PPARα, PPARδ and PPARγ have been reported to correlate with depression as well." (PMID 40356991, 2025). "Li et.al provided promising and novel evidence that hippocampal PPARδ is an important therapeutic target for depression." (PMID 36142731, 2022). "Administration of PPARδ antagonist GSK0660 and direct infusion of sh-PPARδ into the brain blocked the effects of telmisartan on the improvement of depression-like behavior in these mice." (PMID 29070884, 2017). "Peroxisome proliferator-activated receptor δ (PPARδ) has been introduced as a potential target for depression treatment." (PMID 29070884, 2017). "For further investigation of the interaction between telmisartan and PPARδ in depression, PPARδ antagonist GSK0660 was administered into UCMS mice." (PMID 29070884, 2017). "In conclusion, the obtained results suggest that telmisartan improves symptoms of stress-induced depression in animals under chronic stress through activation of PPARδ." (PMID 29070884, 2017). "Telmisartan was recently shown to activate PPARδ expression; therefore, the effectiveness of telmisartan in treating depression was investigated." (PMID 29070884, 2017). "However, our pathway analysis also revealed that PPARD activation promotes the nitric oxide (NO) formation and ceramide synthesis, which were found to play important roles in the neurobiology of major depression." (PMID 33968145, 2021). "Therefore, PPARδ is involved in the behavioral performance of mice, and telmisartan can promote PPARδ expression to improve depression-like behaviors." (PMID 29070884, 2017). "Our study suggests that hippocampal PPARδ is an important therapeutic target for depression." (PMID 29070884, 2017). "PPARδ could be a novel and promising target for developing new drugs for the treatment of depressive disorders, although more studies are needed to confirm its role of regulation in the depressive behaviors." (PMID 26362775, 2015). "Several previous studies show that PPARD might be involved in depression occurrences." (PMID 33968145, 2021). "These evidences strongly suggest that PPARδ might be involved in depression occurrences." (PMID 26362775, 2015). "Overall, the results of the present study indicate that upregulating hippocampal PPARδ by genetic transfection or a small molecule agonist displays an antidepressive effect and enhances hippocampal neurogenesis in the context of stress, which provides new insight into the neurobiology of depression." (PMID 26362775, 2015). "Telmisartan also reversed the decrease in PPARδ and 5-HTT levels in the hippocampus of depression-like mice." (PMID 29070884, 2017). "In this study, PPARδ was firstly investigated in the chronic mild stress (CMS) and learned helplessness (LH) models of depression." (PMID 26362775, 2015).
depression (continued). "However, no reports on the association of PPARδ with depression have been found yet." (PMID 26362775, 2015). "However, whether PPARδ is involved in depression is unknown." (PMID 26362775, 2015).
Parkinson disease (8 papers, 2011 to 2023). A progressive degenerative disorder of the central nervous system characterized by loss of dopamine producing neurons in the substantia nigra and the presence of Lewy bodies in the substantia nigra and locus coeruleus. "PPARδ and its ligand EA had beneficial effects in the treatment of neuroectodermal tumors and Parkinson's disease and EA has potential anti-cancer and neuroprotective effects." (PMID 37391702, 2023).
primary biliary cholangitis (8 papers, 2018 to 2025). Primary biliary cholangitis (PBC) is a chronic and slowly progressive cholestatic liver disease of autoimmune etiology characterized by injury of the intrahepatic bile ducts that may eventually lead to liver failure. "Although the risk of cancer is uncertain, there is one PPARδ agonist that has undergone clinical trials in primary biliary cirrhosis (PBC)." (PMID 39451206, 2024). "The (patho)physiological roles of PPARδ are understood less, perhaps because the PPARδ-selective agonists were not available clinically until the accelerated approval of seladelpar on 8/14/2024 for the treatment of primary biliary cholangitis." (PMID 40298866, 2025). "Only a PPARδ-selective agonist (seladelpar) is in a clinical trial for treating primary biliary cholangitis (PBC)." (PMID 37627329, 2023).
Cerebral ischemia (7 papers, 2011 to 2021). Restriction of arterial blood supply to the brain associated with insufficient oxygenation to support the metabolic requirements of the tissue. "This suggests that there is increased oxidative stress in PPARδ-null mice following cerebral ischemia." (PMID 22135673, 2011). "It is possible that modulation of these processes contributes to the protective effect of PPARδ after cerebral ischemia." (PMID 22135673, 2011). "Additionally, PPARδ agonists appear to be protective after cerebral ischemia; rats given infusions of L-165041 or GW501516 had significantly attenuated ischemic damage 24 h after MCAO." (PMID 22135673, 2011).
ischemia (7 papers, 2008 to 2022). A hypoperfusion of the BLOOD through an organ or tissue caused by a PATHOLOGIC CONSTRICTION or obstruction of its BLOOD VESSELS, or an absence of BLOOD CIRCULATION. "PPARδ may regulate these responses by decreasing activity of matrix metalloproteinases (MMPs), enzymes that degrade structural proteins in the extracellular matrix and that have been implicated in ischemia-induced parenchymal and vascular damage." (PMID 22135673, 2011). "In a mouse model of ischemia-induced cerebral injury, PPARδ (peroxisome proliferator-activated receptorδ) was identified as a regulator of miR-15a that inhibits the induction of apoptosis by preventing miR-15a expression." (PMID 24887070, 2014). "The difference in infarct size was detected as early as 30 min after induction of ischemia, suggesting that PPARδ plays an early role in protection." (PMID 22135673, 2011). "Our findings demonstrated that a multi-component Chinese medicine DHI effectively increased blood flow recovery after tissue ischemia in diabetic mice by promoting angiogenesis and improving glucose tolerance through a concomitant activation of VEGF-A/VEGFR-2 and PPARδ signaling pathways." (PMID 27930695, 2016).
leukemia (7 papers, 2014 to 2025). A malignant (clonal) hematologic disorder, involving hematopoietic stem cells and characterized by the presence of primitive or atypical myeloid or lymphoid cells in the bone marrow and the blood. "The promyelocytic leukemia (PML)–peroxisome proliferator-activated receptor-delta (PPAR-delta)–fatty-acid oxidation (FAO) pathway is another pathway which is important in HSC maintenance." (PMID 24931005, 2014). "Indeed, HSCs lose their reconstitution capacity by knocking down promyelocytic leukemia (Pml)-regulated peroxisome-proliferator activated receptor delta (Ppar-δ)." (PMID 36290314, 2022).
liver cancer (7 papers, 2020 to 2025). An epithelial or non-epithelial malignant neoplasm that arises from the liver. "Functional assays showed that PPARD is essential for the proliferation and migration of liver cancer cells." (PMID 38652093, 2024). "Based on these results, we can surmise that PPARD promotes the proliferation and migration of liver cancer cells." (PMID 38652093, 2024). "Through cellular function experiments, the study verified that PPARδ could stimulate liver cancer cell proliferation, migration, and angiogenesis by activating the PI3K/AKT/GSK-3β signaling pathway." (PMID 39156976, 2024). "Our data indicate that m1A inhibitors combined with PPARδ antagonists may be an effective therapy for liver cancer." (PMID 34728628, 2021). "Herein we show that PPARδ is a pro-tumor factor in liver cancer development." (PMID 34728628, 2021). "Finally, wound healing assay confirmed that PPARD can promote the migration of liver cancer cells." (PMID 38652093, 2024). "Parallelly, DKO in MycOE mice also displayed suppression of liver cancer development compared to littermate control mice.Trmt6/Trmt61a DKO reduced levels of m1A, Pparδ, and Hmgcs2 in MycOE or DEN induced liver tumor tissues." (PMID 34728628, 2021). "The CCK8 assay revealed that the proliferation of liver cancer cells was significantly reduced after PPARD knockdown compared to that in the negative control group, and the results were consistent for both cell lines (p < 0.01)." (PMID 38652093, 2024). "However, the role and mechanism of PPARδ in the regulation of liver CSC self-renewal and liver cancer development remain unclear." (PMID 34728628, 2021).
lung adenocarcinoma (7 papers, 2021 to 2025). A carcinoma that arises from the lung and is characterized by the presence of malignant glandular epithelial cells. "We have analyzed the expression of PPARD in lung adenocarcinoma (LA) and squamous cell carcinoma (LSCC) datasets." (PMID 35342393, 2022). "By differential expression analysis and LASSO logistic regression analysis we constructed an 8-gene (IKBKB, LTBR, MIF, PPARD, PPIA, PSME3, S100A6, SEMA4B) based risk score model to predict lymph node metastasis in lung adenocarcinoma." (PMID 34109216, 2021). "Additionally, pairwise analysis revealed that high expression of CXCR4, β-catenin, and PPARδ correlated positively with 75 human lung adenocarcinoma tissues, which was predictive of poor prognosis." (PMID 33637678, 2021).
non-small cell lung carcinoma (7 papers, 2012 to 2023). A group of at least three distinct histological types of lung cancer, including non-small cell squamous cell carcinoma, adenocarcinoma, and large cell carcinoma. "One study demonstrated that PPARδ promoted proliferation and inhibited apoptosis through the PI3K-AKT pathway in non-small cell lung cancer." (PMID 35151320, 2022). "Specific biological and clinical roles of PPARδ in non-small cell lung cancer (NSCLC) is not fully explained." (PMID 34921177, 2021).
Arthritis (6 papers, 2018 to 2023). Inflammation of a joint. "Notably, expression of PPARδ in mouse MSCs has been shown to impair MSC efficacy in a mouse model of arthritis, while knockdown or antagonism of PPARδ-enhanced mouse MSC efficacy via increased nitric oxide (NO) production." (PMID 34831203, 2021).